LINC00163 (long independently transcribed non-coding RNA 163)
Synonyms: NLC1-A; NLC1A; C21orf134; NCRNA00163
Gene: Long non-coding RNA gene on chromosome 21 (44,989,864 to 44,994,086, reverse strand). Ensembl gene ENSG00000234880.
Diseases named in the same sentence as LINC00163 in open-access papers:
LINC00163 is named in the same sentence as 1 disease in open-access papers, as found by Europe PMC text mining. Sharing a sentence is not in itself a finding about the gene and the disease.
LINC00163 shares sentences with these, for which no sentence is quoted: cancer (1 paper).